SHMT2 (serine hydroxymethyltransferase 2)
Diseases named in the same sentence as SHMT2 in open-access papers (continued):
Sharing a sentence is not in itself a finding about the gene and the disease.
cancer (continued). "While maintaining its capacity to inhibit mitochondrial oxidative phosphorylation, metformin lost its cytotoxic and antiproliferative activity in SHMT2-null cancer cells unable to produce energy-rich NADH or FADH2 molecules from tricarboxylic acid cycle (TCA) metabolites." (PMID 34439169, 2021). "Furthermore, we examined the correlation between SHMT2 and β-catenin expression with cancer progression and patient survival." (PMID 33456583, 2021). "Moreover, impaired cancer cell proliferation due to the inhibition of SHMT2-induced metabolic reprogramming was further validated in animal models." (PMID 34476002, 2021). "Overall, these findings suggest that, while partially maintaining its capacity to inhibit mitochondrial OXPHOS activity, metformin loses its cytotoxic and antiproliferative activity in SHMT2-null cancer cells unable to produce energy-rich NADH or FADH2 molecules from TCA cycle substrates." (PMID 34439169, 2021). "SHMT2 was found to be significantly increased in a variety of cancers, including colorectal cancer." (PMID 34200820, 2021). "Our demonstration of metformin as a PLP-competitive inhibitor of SHMT2 oligomerization might open new horizons for understanding the anti-cancer behavior of metformin." (PMID 34439169, 2021). "Their high levels of expression in cancer cells may reflect their regulation by MYC as MYC binds to the SHMT2 and MTHFD2 gene promoters, along with that for MTHFD1L." (PMID 35008360, 2021). "SHMT2 is highly upregulated in diverse cancer types, correlated with poor outcomes, and may support tumor aggressiveness by enhancing mitochondrial functions, including redox balance and nucleotide synthesis." (PMID 33637676, 2021). "SHMT2 is upregulated in cancers to support tumor cell proliferation." (PMID 33990700, 2021). "However, one should acknowledge that anti-cancer models that disrupt SHMT2 as a proxy for drug treatment likely overestimate the undesirable impact of SHMT2 targeting." (PMID 34439169, 2021). "The identification of selective SHMT2 inhibitors could be an innovative and promising approach for the treatment of various cancers." (PMID 34476002, 2021). "SHMT2 was significantly elevated in more than 85% of cancer types compared with normal tissues." (PMID 34476002, 2021). "Targeting SHMT2 disturbs the homeostasis of NADP/NADPH pool which is important in cancer survival." (PMID 32111066, 2020). "Besides these studies, a recent research also reported that SHMT2 desuccinylation is a pivotal signal in cancer cells to adapt serine metabolic processes for rapid growth." (PMID 33066813, 2020). "When SHMT2 was inhibited, the proliferation of cancer cells was subsequently inhibited." (PMID 33163414, 2020). "Hence, the role and correlation of SHMT2 in the OSCC microenvironment possibly promote cancer cell growth in OSCC and lead to the poor prognosis of OSCC patients." (PMID 33163414, 2020). "Furthermore, western blot of whole-cell extract from different types of cancer cells detected a band with the expected molecular weight of SHMT2 and whose intensity was substantially increased upon treatment of cells with NAM." (PMID 30367038, 2018). "MTHFD2 has potential for cancer therapy as a promising drug discovery target compared with SHMT2." (PMID 30582043, 2018). "However, more effective and specific SHMT2 inhibitors for therapeutic intervention in various cancers need to be developed." (PMID 30367038, 2018). "Moreover, recent studies have shown that SHMT2 expression level is generally higher than normal tissues in a variety of cancer and it plays crucial roles in cancerous cell growth and aggressiveness." (PMID 30228815, 2018).
cancer (continued). "Highly qualified oncogenomics have identified SHMT2 as a potential cancer driver gene." (PMID 30228815, 2018). "PSAT1, PHGDH, and SHMT2 are three key enzymes in the serine and glycine pathway and enhanced serine and glycine biosynthesis provides sufficient precursors for the synthesis of proteins, nucleic acids, and lipids for highly proliferating cancer cells." (PMID 28693523, 2017). "SHMT2 has been shown to drive cancer cell growth in different contexts." (PMID 27635066, 2016). "Interestingly, the metabolic activity of SHMT2 has been shown to strongly correlate with the rates of proliferation across the NCI60 cancer cell collection." (PMID 28040803, 2016). "SHMT2 is the mitochondrial form of a pyridoxal phosphate-dependent enzyme that catalyzes the reversible reaction of serine and tetrahydrofolate to glycine and 5,10-methylene tetrahydrofolate and recently shown to be a potential cancer driver gene." (PMID 25902260, 2015). "While the mitochondrial isoform of SHMT (SHMT2) has recently been identified as an important player in the control of cell proliferation in several cancer types and as a hot target for anticancer therapies, the role of the cytoplasmic isoform (SHMT1) in cancerogenesis is currently less defined." (PMID 25412303, 2014). "The lower intracellular levels of serine and glycine in cancer cells that we observed in vitro indicate a high turnover with increased consumption and usage of these amino acids in downstream biosynthetic pathways, which is supported by the enhanced SHMT2 expression in response to RT." (PMID 38160212, 2024). "All these studies confirmed that SHMT2 could serve as a promising target for cancer treatment." (PMID 36213384, 2022). "The high activity of SHMT2 could help cells resist the pressure of reactive oxygen species in the mitochondria and ensure the supply of biological macromolecules in cells, thereby aggravating the malignant proliferation of cancer cells." (PMID 36110969, 2022). "Interestingly, the molecular modeling studies with hydroxymethyltransferase 2 (SHMT2), a protein that is upregulated in lung and other cancers, revealed that the active hybrids 4b and 4c displayed comparable-to-superior binding affinity than ligand 8Z1, a pyrazolopyran inhibitor." (PMID 34109154, 2021). "However, in the context of cancer cell lines with high mitochondrial SHMT2 flux, activity of GCS is necessary to clear excess glycine and prevent a build-up of the toxic byproducts aminoacetone and methylglyoxal derived from the interconversion of glycine and threonine." (PMID 33669382, 2021). "Therefore, we examined whether SHMT2 inhibition affects the proliferation and survival of cancer cells." (PMID 33637676, 2021). "However, the function and mechanism underlying the nonmetabolic activity of SHMT2 in cancer remains largely unclear." (PMID 33456583, 2021). "These work suggested that SHMT2 may be a potential therapeutic target for cancer patients." (PMID 33863325, 2021). "SHMT2 could be acetylated at lysine K95 in different cancer cells, including CRC cells." (PMID 34476002, 2021). "Current studies showed that SHMT2 may be participated in several kinds of cancer." (PMID 33066813, 2020). "Hence, SHMT2 is linked to several aspects of metabolism important to cancer cell survival and proliferation but is not established as a cancer drug target." (PMID 32903271, 2020). "Therefore, SHMT2 is a potential target in cancer therapeutics." (PMID 32111066, 2020). "However, in recent years, it was reported that C1 metabolism in the mitochondria was markedly enhanced in a comprehensive gene analysis of cancer cell lines and tumor tissues of cancer patients, such as serine hydroxymethyltransferase 2 (SHMT2) and methylenetetrahydrofolate dehydrogenase 2 (MTHFD2)." (PMID 30582043, 2018). "Therefore, inhibition of SHMT2 activity by leucovorin could also account for the anti-cancer effects." (PMID 30367038, 2018).
cancer (continued). "Furthermore, high SHMT2 in cancer cells creates a dependency on glycine clearance that could be exploited for anticancer therapy." (PMID 27635066, 2016). "In cancer, SHMT1 sometimes acts as a tumor suppressor, modulating redox homeostasis and inhibiting metastasis, whereas SHMT2 often supports tumor proliferation and survival by enhancing nucleotide biosynthesis and metabolic flexibility." (PMID 40738465, 2025). "SHMT1 and SHMT2, which are key enzymes in OCM, play distinct yet interconnected roles in cancer progression and metabolic disorders." (PMID 40738465, 2025). "Across various cancer types, SHMT1 and SHMT2 exhibit distinct expression patterns and isoform-specific functional roles." (PMID 40738465, 2025). "Existing research reports have demonstrated through molecular and cellular experiments that SHMT2 is involved in regulating signaling pathways such as cell cycle, redox, apoptosis, and ECM, which affect the proliferation and apoptosis of cancer cells." (PMID 41347062, 2025). "Stable isotope tracing studies have demonstrated that SHMT2 enhances mitochondrial OCM by facilitating serine-to-glycine conversion, enabling cancer cells to survive under metabolic stress." (PMID 40738465, 2025). "We observed elevated expression levels of SHMT2 and MTHFD2 genes in cancer cells compared to normal cells (p-values < 0.001)." (PMID 38331894, 2024). "As SHMT2 is the main cancer-related enzyme responsible for ser/gly conversion and downstream synthesis of the pyrimidine nucleotide TMP, we measured SHMT2 protein expression by flow cytometry in response to irradiation across a NSCLC cell panel (n = 6)." (PMID 38160212, 2024). "SHMT2 and MTHFD2, regarded as oncogenes, are significantly upregulated in various cancer types and promote cancer cell survival." (PMID 38279895, 2024). "Targeting both SHMT1 and SHMT2 is essential for SHIN1/2, AGF347 and other compounds to exert potent anti-cancer effects." (PMID 37664062, 2023). "Many one carbon metabolic enzymes, including SHMT2, MTHFD2, and ALDH1L2, are highly expressed in human cancers, but how their activities are regulated is poorly understood." (PMID 37507016, 2023). "This comes with a further cost to cancer cells: when de novo serine synthesis is inhibited by a pharmacological inhibitor of the first enzyme of the SSP, PHGDH, serine utilization by SHMT2 is reduced." (PMID 37949226, 2023). "The mitochondrial isoforms of folate cycle enzymes serine hydroxymethyl transferase and methylene-tetrahydrofolate reductase (SHMT2 and MTHFD2) are very important targets for drug development in cancer therapy." (PMID 37233697, 2023). "Recent studies have led to the development of chemical inhibitors specifically targeting SHMT2 and MTHFD2, potentially promising as treatments to impair proliferation and aggressiveness of cancer cells." (PMID 36964165, 2023). "The majority of the proteins downregulated by miR-423-5p are involved in the pentose phosphate pathway, glycolysis, and carbon metabolism in cancer (G6PH and LDHA), as well as the biosynthesis of amino acids (SHMT2 and ASNS)." (PMID 36614061, 2022). "Serine hydroxymethyltransferase 2 (SHMT2) and MTHFD2 were indeed among the most overexpressed metabolic genes in nineteen different cancer types analyzed." (PMID 35831624, 2022). "Serine hydroxymethyltransferase 2 (SHMT2) catalyzes the conversion of serine and glycine to support the proliferation of cancer cells." (PMID 35392171, 2022). "The active hybrids were docked to understand their interaction with human serine hydroxymethyltransferase 2 (SHMT2), a protein that is upregulated in lung and other cancer cells." (PMID 34109154, 2021). "SHMT2 can be deacetylated by SIRT3 and SIRT5 at Lys 95 and 280, respectively, increasing enzymatic activity and driving cancer cell proliferation." (PMID 33990700, 2021).
cancer (continued). "Given that the SHMT2 and MTHFD2 genes are attractive targets for cancer therapy, small-molecular inhibitors have been developed to target the folate pathway of 1C metabolism, some of which have been studied in preclinical and clinical trials." (PMID 34298902, 2021). "In our study, we found that SHMT2 is a common target substrate of LONP1 and ClpP for cancer cell survival." (PMID 33637676, 2021). "Serine hydroxymethyltransferase 2 (SHMT2) converts serine plus tetrahydrofolate (THF) into glycine plus methylene-THF and is upregulated at the protein level in lung and other cancers." (PMID 32903271, 2020). "A meta-analysis also found that SHMT2 and its downstream enzyme MTHFD2 were broadly required for cancer cell proliferation and viability." (PMID 33066813, 2020). "Serine hydroxymethyltransferase 2 (SHMT2) converts serine to glycine in mitochondria and is upregulated in a variety of cancers." (PMID 30367038, 2018). "It was demonstrated that mitochondrial 1C enzymes, serine hydroxymethyltransferase (SHMT2) and methylene tetrahydrofolate dehydrogenase (MTHFD2), are highly over-expressed in cancer cells." (PMID 29342092, 2018). "The integrated analysis identified glycine consumption as well as expression of the mitochondrial glycine biosynthetic pathway (SHMT2, MTHFD2 and MTHFD1L) to be strongly correlated with the rates of proliferation across all cancer cell lines." (PMID 28177894, 2017). "Patients of HER2-positive and HR-negative breast cancer had increased SHMT2 and ASCT2 levels compared to patients with luminal-like cancer." (PMID 29020998, 2017). "Mitochondrial enzymes SHMT2 and MTHFD2 are the key components of the folate cycle and their deregulation plays a pivotal role in the cancer-related one-carbon metabolism." (PMID 28177894, 2017). "TYMS, SHMT2, and DHFR genes of one carbon metabolism are proven to contribute to genome instability and cancer development." (PMID 29312619, 2017). "Their impact on cancer-related metabolism is very high; moreover, SHMT2 and MTHFD2 are preferentially expressed in quickly proliferating cells including cancer." (PMID 28177894, 2017). "Accumulating evidence positions SHMT2 and methylenetetrahydrofolate dehydrogenase 2 (MTHFD2) — the first and second enzymes in mitochondrial serine catabolism — as independent prognostic markers and potential therapeutic targets across multiple cancer types." (PMID 40265021, 2025). "Additionally, SHMT2 synergizes with mitochondrial proteases LONP1 and ClP to maintain mitochondrial protein homeostasis and enhance cancer cell survival." (PMID 40738465, 2025). "SHMT2 and MTHFD2 are among the most consistently upregulated metabolic genes in cancer, supporting the critical role of one-carbon metabolism in the production of metabolites to fuel rapid growth and cell division and to survive intra- and extracellular oxidative stress." (PMID 40698729, 2025). "Something that has been of interest in cancer studies is that SHMT2, but not SHMT1, has been highly expressed in a variety of cancers, and the inhibition of SHMT2 has also been shown to suppress tumor growth and malignancy." (PMID 39189649, 2024). "Thus, SHMT2 and MTHFD2 are potential targets for cancer treatment due to their specific expression and prognostic value, which attract considerable attention." (PMID 38279895, 2024). "Especially enzymes of the mitochondrial one-carbon metabolism, SHMT2 and MTHFD2 are frequently increased in cancers, however, cancer cells can partly switch to the cytoplasmic isoforms for the generation of methylene-THF and thus the generation of one-carbon units." (PMID 38515202, 2024). "Given that SHMT2 and MTHFD2 are overexpressed in cancer, mitochondrial 1C metabolism inhibitors might be more selective than cytosolic antifolates like methotrexate." (PMID 38431691, 2024).
cancer (continued). "GLDC inhibition impaired cancer cells survival with high SHMT2 levels due to an excess of glycine, not metabolized by GLDC, which is thus converted to toxic molecules (aminoacetone and methylglyoxal)." (PMID 37298093, 2023). "According to the analysis of TCGA-ESCA data, we found that the expression of serine hydroxymethyltransferases 1, 2 (SHMT1, SHMT2) and glycine decarboxylase (GLDC), which catalyze the conversion of serine to glycine, were upregulated in ESCC cancer tissues compared with normal tissues." (PMID 36756157, 2023). "Many of these models have examined the drivers of proliferative capacity in cancer cells, which exhibit higher levels of SHMT2 than noncancer tissue." (PMID 36959541, 2023). "In addition, the silencing of SHMT2 in OSCC cells can affect cell cycle regulatory factors and induce cell G1 phase arrest, resulting in decreased cancer cell growth as well as inhibited cancer proliferation in vivo." (PMID 36566175, 2022). "Inversely, the transfection of UTR2 in cancer cells can also modulate SHMT1 activity and reduce cell viability, suggesting that it is of great necessity for us to give more studies on the relationship between SHMT1 and SHMT2." (PMID 35531073, 2022). "Targeting PHGDH, SHMT2, or other enzymes in the one-carbon metabolic pathway has not yet been proven to slow or halt tumor development in genetically modified, patient-derived xenografts (PDX), or syngeneic animal models of cancer." (PMID 36358687, 2022). "Aberrant SHMT2 and MTHFD2 expression might impair DNA synthesis and damage redox balance, which is important for cancer cell survival." (PMID 36551330, 2022). "Next, we focused on the correlation between SHMT2 and cancer cell stemness in both in vitro and in vivo experiments, and demonstrated for the first time that SHMT2 promotes the progression of HNC by promoting cancer cell stemness." (PMID 36077112, 2022). "In replete environments, serine catabolism by SHMT2 can occur in excess and release of glycine and formate, termed “formate overflow”, has been reported for several cancer and non-transformed cell lines and in mice." (PMID 33669382, 2021). "This is not surprising, as elevated SHMT2 expression has been observed in various human cancers, and clinically, cancer patients with high SHMT2 expression show poorer survival outcomes than those with low expression." (PMID 33456583, 2021). "Treatment of cancer cells with metformin similarly promotes a build-up of IMP biosynthetic intermediates such as formimino-THF, suggesting the impairment of its further metabolism by SHMT2." (PMID 34439169, 2021). "Next, in vitro experiments were performed to investigate the cellular effects of SHMT2 on non-resistant and resistant cancer cells." (PMID 31894856, 2020). "Increased SHMT2 decreases cytosolic levels of serine and phosphoribosylaminoimidazolesuccinocarboxamid (SAICAR), two activators for pyruvate kinase 2 (PKM2), which allows redistribution of glycolytic carbons in support of cancer cell proliferation." (PMID 32903271, 2020). "SHMT2 knockdown leads to decreased NADPH and impaired cancer survival." (PMID 32111066, 2020). "When exposed to paclitaxel, cancer cells activated the EIF2AK3/EIF2AK4‐pEIF2S1‐ATF4 axis and maintained redox homoeostasis by inducing expression of the major antioxidant enzymes HMOX1, SHMT2 and SLC7A11." (PMID 31211507, 2019). "Although SHMT2 inhibitors have not been applied in cancer therapy, some chemotherapy drugs targeting SHMT2 downstream enzymes, in one-carbon metabolism such as 5-FU and gemcitabine, have significantly shown a dramatic response in subsets of cancer patients." (PMID 30228815, 2018). "Strikingly, SHMT2 but not SHMT1 expression is significantly upregulated in a variety of cancers, including colorectal, brain, central nervous system (CNS), kidney, and bladder cancers." (PMID 30367038, 2018).